TNF (tumor necrosis factor)
Diseases named in the same sentence as TNF in open-access papers (continued):
Sharing a sentence is not in itself a finding about the gene and the disease.
uveitis (continued). "Much less evidence is available in the setting of JIA; thus, we believe it is timely to conduct an extensive literature review about the potential relationships between JIA, uveitis, MS and TNF-α inhibitors." (PMID 36009588, 2022). "Biotherapies with anti-tumor necrosis factor alpha (anti-TNFα) are effective in controlling inflammation for severe pediatric uveitis in recent studies." (PMID 35311049, 2022). "Nevertheless, since inhibition of DHODH also impedes B cell activation, the therapeutic effect of KIO-100 (PP-001) exceeds an exclusive T cell suppression as gained by the presently approved therapies for uveitis, ciclosporin A and TNF-blocker Adalimumab." (PMID 36325389, 2022). "Although there are no randomized clinical trials comparing the efficacy ofinfliximab and adalimumab in uveitis, there are many retrospective andobservational studies juxtaposing the two anti-TNF-a agents." (PMID 35765634, 2022). "The levels of EGF, fractalkine, IL1-β, IL-17A, IL-1RA, IL-2, IL-23, IL-8, IP-10, TNF-α and IL-6 in patients with uveitis in their active phase were independent to their counterpart levels in plasma, the difference being statistically significant (p < 0.05)." (PMID 36498608, 2022). "A similar effect on leukocyte adhesion was also reported by others after TNF-α blockade in LPS-induced uveitis in normal mice." (PMID 35628515, 2022). "The effectiveness of Anti-TNF-alpha for treating refractory uveitis has been demonstrated in clinical trials and case series." (PMID 35979409, 2022). "The pro-inflammatory cytokine tumor necrosis factor α (TNFα) has been found at elevated levels in the aqueous humor of patients with uveitis, and TNFα blockade shows efficacy in animal models of uveitis." (PMID 35704329, 2022). "Analysing their outcomes, they showed increased levels of TNF-α and IL-6 in four out of five eyes with uveitis, which is contradictory to our study." (PMID 36498608, 2022). "Although uveitis represents a group of intraocular inflammatory conditions with distinct phenotypic heterogeneity, its common feature is increased expression of TNF-α in both the serum and aqueous humor." (PMID 34795583, 2021). "Incidence of uveitis was lower with anti-TNF mAb versus placebo (OR = 0.46; CI 95% [0.24; 0.90]) and versus anti-IL17A (OR = 0.34; CI 95% [0.12; 0.92]." (PMID 34271991, 2021). "These experiments have verified that the TNF-α signaling pathway is related to the pathogenesis of experimental uveitis, especially the NF-κB pathways." (PMID 34795583, 2021). "EchA possesses potent antioxidant, antimicrobial, anti-inflammatory, and chelating abilities, and has been reported to ameliorate LPS-induced uveitis by reducing ROS production, NF-κB expression, and TNF-α expression." (PMID 33922418, 2021). "Upregulation of TNFα is found in several inflammatory eye diseases including RP, glaucoma, uveitis, retinal vascular tumors, Adamantiades–Behcet disease, diabetic macular edema, DR, or AMD." (PMID 33672611, 2021). "Other TNF inhibitors, such as golimumab and certolizumab pegol, showed promising results, but to date, only adalimumab is indicated for uveitis treatment." (PMID 34631754, 2021). "As is the case with steroids, antibiotics, or biologics including anti-INF-γ, anti-IL-2 (daclizumab), TNF-α (etanercept, infliximab, adalimumab), IL-12/IL-23 antagonist (ustekinumab) that have also been used in uveitis, these drugs are for short-term use." (PMID 34603297, 2021). "↓ uveitis.↓ neutrophils, T and B cells, M1 macrophages infiltration↓ TNF-α, CXCL8, and RANTES in the eye." (PMID 34868025, 2021). "The phase 2, single-arm (adaptive-trial), open-label APTITUDE trial evaluated the efficacy and safety of the fully humanized anti-interleukin (IL)-6R antibody, tocilizumab, with MTX in anti-TNF refractory JIA-uveitis." (PMID 34627340, 2021). "According to the P-score, the ranking from the most to the least preventive treatment of uveitis flare was as follows: anti-TNF mAb, ETN, placebo, and anti-IL17A." (PMID 34271991, 2021).
uveitis (continued). "Uveitis presents high levels of TNF-α in intraocular fluids which is directly proportional to CD4 + Th cells activation, leading to potentially irreversible tissue damage." (PMID 33634341, 2021). "Inflammatory cytokines, such as IL-6, which transduces cell signaling through the JAK/STAT pathway, and TNF, whose expression is reduced by inhibition of JAK1 and JAK2, are considered to be associated with the pathology of JIA-uveitis and ANA-positive uveitis." (PMID 34627340, 2021). "Among these adalimumab (ADA), a fully humanised antibody against TNF-α and the only TNF-α inhibitor approved for uveitis as of 2021, has become the drug of choice." (PMID 34419092, 2021). "Anti-TNF drugs, such as infliximab and adalimumab, can successfully control uveitis flares, whereas etanercept can promote a paradoxical uveitis." (PMID 34631754, 2021). "The regulation of various signaling components in the TNF-α signaling pathways also seems to be promising for controlling the progression of uveitis when there is a poor response to TNF-α-agents." (PMID 34795583, 2021). "Therapeutic strategies have evolved over the last few years, and anti-TNF-α agents have become well accepted for the treatment of refractory uveitis." (PMID 34795583, 2021). "Thirty nanometers cit-AuNP topically applied reduced the enhanced TNFα concentration in aqueous humor of rats 24 h after LPS-induced uveitis compared to saline-treated rats." (PMID 33608025, 2021). "The use of anti-TNFα agents improves the survival of retinal cells in animal models of glaucoma, uveitis, DR, choroidal neovascularization, and RP." (PMID 33672611, 2021). "This outcome suggested that TNF-α is involved in the pathogenesis of uveitis and its potential use as a therapeutic drug to reduce ocular inflammation." (PMID 34795583, 2021). "Methotrexate (MTX) is then prescribed in most cases; however, some patients also need anti-tumor necrosis factor alpha monoclonal antibody therapy and, in some cases, other biologics to control uveitis and avoid long-term ocular damage." (PMID 34208973, 2021). "The TRAF1/C5 variants are located near genes encoding for the complement component 5 and the TNF-receptor associated factor 1, a negative regulator of the TNF pathway, underscoring the role of TNF signaling in JIA associated uveitis." (PMID 34438537, 2021). "Anti-TNFα therapy is effective as a treatment for severe sight-threatening uveitis, both in patients with ocular BD and in idiopathic endogenous uveitis." (PMID 33671954, 2021). "In patients with active uveitis or uveitis animal models, TNF-α levels in serum and aqueous humor are elevated, which is correlated with disease status." (PMID 34795583, 2021). "Psoriatic patients have a higher incidence and prevalence of uveitis, and the involvement of IL-17, IL-23, TNF-α, and IL-6 molecules unite both conditions." (PMID 34829740, 2021). "Over the past decade, studies have increasingly emphasized the effectiveness of anti-TNF-α agents for patients with uveitis." (PMID 34795583, 2021). "Cytokines tumour necrosis factor-alpha (TNFα), interleukin (IL)-6 and monocyte chemoattractant protein-1 (MCP-1) can be produced by activated macrophages during uveitis and are involved in the associated inflammatory responses." (PMID 33671954, 2021). "The role of TNF in the pathogenesis of uveitis has been well-established in animal studies, and the concentration of TNF was also raised in the aqueous humor of patients with uveitis." (PMID 32458144, 2020). "Biological therapy has emerged as a new therapeutic approach in pediatric and adulthood uveitis, based on targeting relevant immunological pathways involved in disease pathogenesis, particularly tumor necrosis factor alpha (TNF-α)." (PMID 32508634, 2020). "For NINAU, anti-TNF-α agents are used as first-line therapy in sight-threatening uveitis, with severe vasculitis or CME, particularly in Behçet’s uveitis." (PMID 33171664, 2020).
uveitis (continued). "Although the remaining anti-TNF therapies are considered off-label for uveitis, they are still used to control ocular inflammation associated with systemic diseases and are specially effective in Behçet’s disease and juvenile idiopathic arthritis." (PMID 32337619, 2020). "Although the exact pathogenesis of uveitis is not completely understood, cytokines such as IL-2, TNF-α, INF-γ, IL-12, and IL-17 have been detected in patients with active disease, and it is believed that they would be key players in the pathogenesis." (PMID 32508634, 2020). "Cytokines were clustered in two major groups: the first one included cytokines with the highest fold difference in concentrations between patients with uveitis and controls: IL-6, IL-8, IFNγ, TNFα, IP-10, G-CSF, IL-1ra." (PMID 32210963, 2020). "The abundance of TNF-α is found in both serum and in sites of inflammation such as oral ulceration, intestinal ulceration, and the aqueous humor of patients with BD uveitis." (PMID 32349254, 2020). "TNF inhibitors began to emerge as a possible therapy for uveitis when a number of large controlled studies indicated that patients with immune-mediated conditions treated with anti-TNF-α agents had a significant decrease in the number of uveitis flares." (PMID 32337619, 2020). "Since enhanced levels of TNFα have been noted in uveitis patients, we have demonstrated that IFNα-C counteracts the effect of TNFα by down-regulating the cytokines and chemokines that are induced by TNFα." (PMID 32101556, 2020). "IP-10, IFNγ, IL-6, G-CSF, TNFα IL-8, IL-1ra, and GM-CSF emerged as the most promising cytokines to be further investigated for treatment of BD- and VKH-associated uveitis." (PMID 32210963, 2020). "A high level of tumor necrosis factor alpha (TNF-α) was found in humor aqueous of uveitis mice models." (PMID 33171664, 2020). "In patients with recurrent or severe uveitis, anti-TNFα monoclonal antibodies should be preferred over ETA." (PMID 32231384, 2020). "The specific presence of IFNγ and TNFα in AH samples only from patients with uveitis renders these cytokines promising targets in a therapeutic perspective." (PMID 32210963, 2020). "This was a multicenter single-arm study including 21 patients with active uveitis, refractory to anti-TNF-α agents." (PMID 33171664, 2020). "Currently, biologic agents of anti-TNF-α and anti-IL-6 receptor antibodies are widely used for uveitis treatment with satisfying clinical outcomes." (PMID 32117217, 2020). "The most common therapies for treating uveitis are general anti-inflammatory drugs like corticosteroids, immunosuppressives such as cyclosporine-A, methotrexate, and mycophenolates, and anti-TNFα agents, such as Humira." (PMID 32708100, 2020). "Golimumab has been found effective in uveitis resistant to local treatments, general first-line treatments, and in some cases, other TNF-α inhibitors (TNFi)." (PMID 32336278, 2020). "Patients were treated with SSZ (n = 26, 68.4%), MTX (n = 11, 28.9%) and anti-TNFα agents (n = 13, 34.2%); because of recurrent and/or severe uveitis (n = 22, 57.9%), inflammatory rheumatism (n = 11, 28.9%) or for both (n = 5, 13.2%)." (PMID 32231384, 2020). "Biologic agents are considered to be appropriate alternatives for treatment in steroid-refractory sarcoidosis and uveitis due to the role of tumor necrosis factor (TNF) in mediating the inflammatory cascade seen in both conditions." (PMID 32782876, 2020). "Anti-TNF-α, considered the first-line biological agent recommended in the treatment of uveitis, has proven remarkably effective." (PMID 31523783, 2019). "His treatment included NSAIDS, intraarticular steroids injections, Methotrexate (MTX) and TNF inhibitors as well as steroid eye drops for the uveitis." (PMID 31847838, 2019).
uveitis (continued). "In the current era of pharmacotherapy for uveitis, we can theoretically target TNF, IL-1, IL-12/IL-23, IL-6, IL-17, CTLA4, CD20, etc.—various cytokines that have been identified in the serum and eyes of patients with different types of uveitis." (PMID 31523783, 2019). "Among the 6 patients receiving anti-TNF-alpha therapy, we used adalimumab for the two patients with uveitis based on our experience in the treatment of uveitis in juvenile idiopathic arthritis." (PMID 31296171, 2019). "More specific therapies, including the administration of TNF blockers, have recently been introduced for uveitis treatment." (PMID 31335861, 2019). "The findings from several studies that have evaluated the effectiveness and safety of anti-TNF-alpha therapy in adult BD patients with refractory uveitis, have shown symptom improvements in 43.5–67.7% of the patients." (PMID 31296171, 2019). "The proinflammatory cytokine tumor necrosis factor α (TNF-α) is thought to play a key role in uveitis inflammation, and aqueous humor and serum levels of TNF-α are upregulated in patients with uveitis." (PMID 30881221, 2019). "Cytokines like TNF-α have been shown to play a role in the pathogenesis of uveitis, as evidenced by elevated TNF-α levels in the aqueous humor." (PMID 31783768, 2019). "Biologics, especially anti-TNF alpha agents, are some of the viable options for treating sight-threatening uveitis." (PMID 31367810, 2019). "Data from systematic review showed that remission rate with anti-TNF alpha agents use is as high as 60–100% in 369 adult patients with BD-related uveitis." (PMID 31367810, 2019). "In particular, ocular inflammation (uveitis) has been reported as a major paradoxical effect from treatment with anti-TNF-α antibody." (PMID 31620105, 2019). "In recent years, various studies have shown that adult patients suffering from sight-threatening BD-uveitis were successfully treated with anti-TNF alpha drugs." (PMID 31367810, 2019). "They found higher levels of IL-1β, IL-4, IL-17A, IL-17F, IL-21, IL-22, IL-31, IFN-γ, sCD40L, and TNF-α, with a significant difference for IL-17F, in BD-recurrent uveitis patients respect to the BD-remitted uveitis group, before drug infusion." (PMID 31134098, 2019). "Infliximab and adalimumab, both anti-TNF alpha antibodies, have been reported to successfully control BD-related uveitis." (PMID 31367810, 2019). "After that report, several case series have demonstrated efficacy of tocilizumab in the treatment of uveitis refractory to anti-TNF agents." (PMID 31523783, 2019). "Since the initial phase, the AnxA12–26 was able to reduce the expression of IL-1β, INF-γ, IL-6, TNF-α, and IL-17, corroborating studies with in vivo and in vitro models of retina autoimmune disease and uveitis in rodents and human." (PMID 30250432, 2018). "These cases had experienced severe uveitis attacks during the all treatment period, before anti-TNF-α agents was started." (PMID 30290779, 2018). "In a longitudinal analysis from a nationwide pediatric rheumatology database the influence of MTX, TNF-α inhibitors, and a combination of the 2 medications on uveitis occurrence in JIA patients was analyzed." (PMID 29996864, 2018). "During uveitis, the use of anti-TNF-α drugs was found to diminish corticoid doses, reduce the number of relapses, and improve disease control in clinical." (PMID 29686615, 2018). "Numerous studies have suggested that anti-TNF-α agents, such as infliximab, are a therapeutic option for the prevention and treatment of uveitis." (PMID 29686615, 2018). "The trial will register at least 22 patients aged 2 to 18 years with active JIA-associated uveitis, who have taken MTX for at least 12 weeks and have failed an anti-TNF agent." (PMID 30886955, 2018).
uveitis (continued). "During experimental uveitis, TNF-α was found to recruit leukocytes to the eye, enhance leukocyte adhesion to the vascular endothelium, activate macrophages and infiltrating T cells, and promote apoptosis of both resident cells and infiltrating cells." (PMID 29686615, 2018). "Efficiently used by rheumatologists, the anti-TNFα biologic treatment has become increasingly important for ophthalmologists in the treatment of uveitis in SpA patients." (PMID 30206554, 2018). "In some uveitis clinics, due to their well documented intense effects to control BU, anti-TNF-α agents’ are being used as a second line therapy after single or combination CIS treatment." (PMID 30290779, 2018). "Topical Curcuma-longa suppressed E. coli lipopolysaccharide-induced uveitis in rats by reducing TNF-α activity." (PMID 28261099, 2017). "We have previously reported that Th2 and Th17 cell-related cytokines; specifically IL-4, IL-10, IL-17A, IL-22, IL-31and TNFα, are exclusively elevated in the vitreous fluid of PDR compared with that of ERM, MH, or uveitis associated with sarcoidosis." (PMID 28558009, 2017). "It is well established that the TNF pathway is a key mediator of inflammation in many ocular diseases including diabetic retinopathy, uveitis, proliferative vitreoretinopathy, macular edema and wet AMD17,66." (PMID 29263354, 2017). "For example, it has been described that this compound diminishes the number of inflammatory cells and TNFα levels in the aqueous humor, in rats with endotoxin-induced uveitis." (PMID 28785262, 2017). "Much of the research to date employing biologic agents for the treatment of uveitis has studied tumour necrosis factor alpha (TNF- α) inhibitors, which have been shown to significantly improve the outcome of uveitis in BD." (PMID 28716038, 2017). "In this case uveitis was refractory to other TNF-α inhibitors, but inflammation resolved after golimumab injections were commenced." (PMID 28716038, 2017). "In this study, TNF-α levels in the aqueous humor during endotoxin-induced uveitis in rats were investigated to further clarify the anti-inflammatory effect of endotoxin tolerance and explore the role of cytokines in this protective mechanism." (PMID 28804726, 2017). "In this study, the incidence of uveitis flares in CZP‐treated axial SpA patients was comparable to rates observed for other anti‐TNF antibodies in AS patients." (PMID 26815944, 2016). "Paradoxical inflammations during anti-TNF-α therapy are defined as adverse effects such as psoriasiform skin lesions, uveitis and sarcoidosis-like granulomas induced by immune reactions, not by infectious agents." (PMID 26864464, 2016). "Here, we report herpetic keratouveitis triggered by treatment with the anti-TNF-α antibody infliximab in a uveitis patient with BD and the failure of the previous trabeculectomy during the course of the infection." (PMID 27800267, 2016). "Incidence of uveitis flares remained low to week 96 and was comparable to rates reported for AS patients receiving other anti–tumor necrosis factor antibodies." (PMID 26815944, 2016). "A retrospective study of patients with spondyloarthropathy further confirms the efficacy of anti-TNF therapy in reducing acute uveitis flares." (PMID 25888248, 2015). "More recent clinical trials have evaluated the use of tumor necrosis factor alpha (TNF-α) inhibitors for the treatment of refractory uveitis." (PMID 30873449, 2015). "The inflammatory process leading to uveitis is mainly driven by Th17 cells and sustained by intricate sceneries directed by many proinflammatory cytokines, chiefly TNF-α and IL-1β." (PMID 25784780, 2015). "The results indicate significant positive benefits of anti-TNF agents to treat uveitis in these patients." (PMID 25888248, 2015). "Remarkably, in a recent United States-based registry analysis of uveitis induced by TNF-α inhibitors, adalimumab accounted for only 3 % of cases, far less than infliximab (24 %) and etanercept (73 %)." (PMID 26044064, 2015).